ENSG00000279686 (novel transcript)
Gene: Protein-coding gene on chromosome 5 (139,442,316 to 139,462,707, reverse strand). Ensembl gene ENSG00000279686.
Genetic constraint (gnomAD): Missense variants: 105 observed, 97.21 expected, observed/expected ratio (o/e) 1.08, 90% interval 0.92 to 1.27. Synonymous variants: 37 observed, 35.04 expected, observed/expected ratio (o/e) 1.06, 90% interval 0.81 to 1.39.